HTR4 (5-hydroxytryptamine receptor 4)
Diseases named in the same sentence as HTR4 in open-access papers:
HTR4 is named in the same sentence as 90 diseases in open-access papers, as found by Europe PMC text mining. Sharing a sentence is not in itself a finding about the gene and the disease. The quoted sentences say what the papers report.
Anxiety (20 papers, 2011 to 2025). Intense feelings of nervousness, tension, or panic often arise in response to interpersonal stresses. "HTR4, a member of the family of serotonin receptors, is widely expressed in multiple brain regions, such as the prefrontal cortex, amygdala, and hippocampus, where it has been associated with mood regulation, depression, and anxiety-related behaviors." (PMID 41295252, 2025).
depression (19 papers, 2011 to 2025). "Changes in 5-HT4R binding were observed in several brain regions in depressed patients while polymorphisms in HTR4 (the gene that encodes 5-HT4R) were associated with a susceptibility to unipolar depression." (PMID 33441982, 2021). "The HTR4 gene in 5q32 encodes a serotonin receptor involved in depression and is strongly expressed in respiratory complex neurons." (PMID 29725345, 2018).
colitis (13 papers, 2012 to 2025). Inflammation of the colon. "Similar study demonstrated a protective effects of 5-hydroxytryptamine receptor 4 agonist against DSS-induced colitis, involving resistance of caco-2 epithelial cells to the detrimental effects of oxidative stress by the free radical donor (H2O2)." (PMID 28951733, 2017). "Other research has reported that the activation of 5-hydroxytryptamine receptor 4 located in intestinal epithelial cells maintains healthy colon motility in mice and guinea pigs, and alleviates inflammation in the colon of mice with colitis." (PMID 38475799, 2024). "We combined the use of an HTR2B agonist (BW723C86) and an HTR4 antagonist (GR113808) to elucidate the mechanism by which HTRs affect the immunoregulatory effects of Trp in mice with Abx pre-exposure and DSS-induced colitis." (PMID 39180723, 2024). "Additionally, tryptophan (Trp) mitigated DSS-induced colitis in mice by upregulating HTR1A and HTR4 expression and downregulating HTR2A expression in the colon." (PMID 39180723, 2024). "On the contrary, all these effects conversed with rectal administration of HTR4 antagonist GR113808, which induced colitis in non-inflamed colons of wild-type mice." (PMID 34502396, 2021).
Constipation (11 papers, 2013 to 2025). Infrequent or difficult evacuation of feces. "TM is used for the treatment of constipation-type irritable bowel syndrome as a HTR4 partial agonist." (PMID 35154317, 2022).
irritable bowel syndrome (8 papers, 2006 to 2025). Irritable bowel syndrome (IBS) is a chronic functional condition of the lower gastrointestinal (GI) tract characterized by abdominal pain or discomfort and disordered bowel habit (diarrhea, constipation, or fluctuation between the two). "Tegaserod (TM) is a serotonin receptor 4 agonist (HTR4) used in the treatment of irritable bowel syndrome (IBS)." (PMID 32085796, 2020).
Chronic constipation (6 papers, 2011 to 2025). Constipation for longer than three months with fewer than 3 bowel movements per week, straining, lumpy or hard stools, and a sensation of anorectal obstruction or incomplete defecation. "The mean medications used to treat chronic constipation mainly include laxatives, stimulant laxatives, surfactants, osmotic agents, guanylate cyclase-C receptor agonists, and 5-hydroxytryptamine receptor 4 (5-HT4) prokinetic agents." (PMID 40337512, 2025).
schizophrenia (6 papers, 2006 to 2025). A major psychotic disorder characterized by abnormalities in the perception or expression of reality. "Intriguingly, our recent study demonstrates that ERVWE1, a significant risk factor in schizophrenia, can inhibit HTR4 expression and contribute to the etiology of schizophrenia." (PMID 37990254, 2023). "Polymorphisms in HTR4 have been associated with bipolar disorder and schizophrenia." (PMID 16507133, 2006). "Intriguingly, data from our lab has demonstrated that ERVWE1 activates the SK2 channel by inhibiting HTR4, which is involved in the development of schizophrenia." (PMID 37990254, 2023). "In addition to HTR1B, other 5-HT receptors, including HTR1A, HTR2A, HTR3, HTR4, and HTR6 are associated with schizophrenia." (PMID 37990254, 2023).
asthma (4 papers, 2013 to 2025). "Among these, we take two genes, WNT3 and HTR4, which are associated with mood swings with lung function, asthma, and COPD." (PMID 41295252, 2025). "According to the available data, HTR2A and HTR2C gene polymorphisms have not yet been incorporated in previous research on asthma, with HTR4 polymorphisms being the only 5-HT receptor gene variants associated with asthma so far." (PMID 37238670, 2023). "Recently, HTR4 SNPs have also been associated with asthma in a Korean population, with the most significant associations localized to introns within HTR4 that were previously identified in the SpiroMeta/CHARGE lung function meta-analyses." (PMID 23890215, 2013). "Peripherally, HTR4 has been identified in smooth muscle cells and bronchial epithelial cells involved in lung development, and it is also associated with lung function, asthma, and COPD." (PMID 41295252, 2025). "For asthma and COPD, one SNP rs11168048 located at 5q32 (harboring HTR4, FBXO38, and SPINK7) and two SNPs rs2122190 located at 5q23.1 (harboring PRR16) and rs6860087 located at 5q32 (harboring HTR4) were identified." (PMID 41295252, 2025). "However, large scale analyses of asthma utilizing 10,365 asthma and 16,110 unaffected controls as part of the GABRIEL study did not identify an association for HTR4 SNPs." (PMID 23890215, 2013).
mood disorder (4 papers, 2011 to 2024). A cognitive disorder a disturbance in which the person's mood is hypothesized to be the main underlying feature. "The surface expression and function of HTR4 are thought to be regulated by the S100 family member p11, which has been implicated in mood disorders and suicide." (PMID 21829518, 2011).
prostate carcinoma (4 papers, 2021 to 2023). A carcinoma that arises from epithelial cells of the prostate gland. "HTR4 performs an important function in human prostate cancer through 5-HT secreted by cancerous tumors and mast cells surrounding the tumors." (PMID 35149954, 2022). "In addition, in prostatic cancer, estrogen may regulate the effect of HTR4 through estrogen receptor β (ERβ) to affect the development of cancer." (PMID 35149954, 2022). "Moreover, the mutations in CNTN5 were reported to contribute to the metastatic process of pancreatic cancer, HTR4 was found predominantly in only high-grade prostate cancer, and the high expression of TEKT3 could be influenced by HBV integration events in liver cancer." (PMID 36816541, 2023). "Genes such as BUB1B, ANX1A1, F5, HTR4, and MUC4 can be used as biomarkers to assist in the diagnosis and prognosis of prostate cancer." (PMID 34512870, 2021).
Anorexia (3 papers, 2014 to 2020). Lack of desire to eat (loss of appetite). "Consistently, stimulation of Htr4 triggers hyperactivity and anorexia." (PMID 32368866, 2020).
bipolar disorder (3 papers, 2006 to 2014). A disorder of the brain that causes unusual shifts in mood, energy, activity levels and the ability to carry out day-to-day tasks. "Several studies have shown that HTR4 polymorphisms could predispose to attention deficit hyperactivity disorder (ADHD) and bipolar disorder, while AUD was strongly associated with both ADHD and bipolar disorder." (PMID 24312204, 2013).
breast carcinoma (3 papers, 2023 to 2025). "Tegaserod maleate, a partial agonist of HTR4, markedly reduced the growth, spread, and migration of breast cancer cells." (PMID 39766808, 2024). "HTR4 was decreased in mucinous breast carcinoma with a FC of 2.645, male breast carcinoma with a FC of 2.237 (TCGA breast statistics) and invasive ductal breast carcinoma stroma with a FC of 6.745 (The Karnoub Breast Statistics)." (PMID 37795441, 2023). "The expression levels of HTR1A, HTR1B, HTR2A, HTR2B, HTR2C, HTR4, and HTR7 were significantly downregulated in highly malignant breast cancer types." (PMID 37795441, 2023). "However, when compared to normal breast tissue, HTR1A, HTR1B, HTR2A, HTR2B, HTR2C, HTR4, and HTR7 were suppressed in high malignancy breast cancer types, whereas they were highly expressed in low malignant breast cancer." (PMID 37795441, 2023).
glioblastoma (3 papers, 2013 to 2024). The most malignant astrocytic tumor (WHO grade IV). "Here, we observed that serotonin receptor 4 (HTR4) was down-regulated in glioblastoma samples, a process that is associated with up-regulation of miR-15b." (PMID 23358700, 2013). "The high expression of HTR1D and HTR2C was negatively related to the OS of HNSC, and almost all the HTGPCR genes, except HTR1B and HTR4, were related to the prognosis of glioblastoma." (PMID 39766808, 2024). "On the other hand, alterations of SGCG, HTR4, ITGB1, CPS1, PROS1 and INPP5A were detected predominantly in anaplastic astrocytoma, while alterations of PDE4D were present in both glioblastoma subtypes." (PMID 24358143, 2013).
glioma (3 papers, 2013 to 2026). A benign or malignant brain and spinal cord tumor that arises from glial cells (astrocytes, oligodendrocytes, ependymal cells). "Alterations of HTR4 gene, frequently present in our set of samples, were not previously detected in glioma." (PMID 24358143, 2013).
colon cancer (2 papers, 2022 to 2025). "Studies have shown that 5-hydroxytryptamine plays a mitogenic role in colon cancer cells, and HTR4 is significantly expressed in both colon cancer tissue and cells." (PMID 35154317, 2022).
congestive heart failure (2 papers, 2012 to 2018). Failure of the heart to pump a sufficient amount of blood to meet the needs of the body tissues, resulting in tissue congestion and edema. "The HTR4 mediates positive inotropic responses to LV dilatation, as seen in post-infarction congestive heart failure." (PMID 30618771, 2018). "The 5-hydroxytryptamine receptor type 4 (HTR4) appears to be the predominant cognate receptor responsible for serotonin responsivity within cardioventricular tissue in experimental models of congestive heart failure." (PMID 30618771, 2018).
epilepsy (2 papers, 2016 to 2024). A brain disorder characterized by episodes of abnormally increased neuronal discharge resulting in transient episodes of sensory or motor neurological dysfunction, or psychic dysfunction. "Finally, we confirmed that the immunoreactivity to serotonin receptor 4 (HTR4) was colocalized in LIN28A-expressing cells, suggesting HTR4 as a potential LIN28A-downstream target in epilepsy." (PMID 38193536, 2024). "Finally, we confirmed that HTR4 immunoreactivity was observed in LIN28A-expressing cells in SGZ at 3 days after SE, suggesting that HTR4 can be a potential LIN28A-downstream target in epilepsy." (PMID 38193536, 2024).
inflammatory bowel disease (2 papers, 2022 to 2024). A spectrum of small and large bowel inflammatory diseases of unknown etiology. "In accordance with this finding, HTR4 agonists alleviate disease severity and reduce inflammation in models of inflammatory bowel disease." (PMID 38256253, 2024).
melanoma (2 papers, 2020 to 2024). A malignant, usually aggressive tumor composed of atypical, neoplastic melanocytes. "For example, tegaserod which is a serotonin receptor 4 (HTR4) agonist is reported to be inducing apoptosis in B16F10 murine melanoma cell line and some human melanoma cell lines by perturbing PI3K/Akt/mTOR pathway." (PMID 38216592, 2024). "Amongst the compounds whose IC50 values were in the low micromolar range, Tegaserod (TM), a serotonin receptor 4 (HTR4) agonist, validated successfully in secondary screening approaches with BRAF WT and BRAFV600E human melanoma cell lines and was pursued in further in vitro and in vivo studies." (PMID 32085796, 2020). "HTR4 mRNA was weakly detected (not detectable in the MeWo cell line) but HTR4 protein expression was undetectable in all melanoma cell lines tested." (PMID 32085796, 2020).
airway hyperresponsiveness (1 paper, 2021). "Mice deficient for this protein (HTR4−/−) were found to have increased airway resistance and exhibit increased methacholine-induced airway hyperresponsiveness." (PMID 34233669, 2021).
Airway obstruction (1 paper, 2013). Obstruction of conducting airways of the lung. "SNPs within HTR4 have been associated with lung function and COPD/airway obstruction in several populations." (PMID 23890215, 2013).
autism (1 paper, 2014). Persistent deficits in social interaction and communication and interaction as well as a markedly restricted repertoire of activity and interest as well as repetitive patterns of behavior. "Htr4 is considered as a putative candidate gene for autism and was found to be differentially expressed in lymphoblastoid cell lines from individuals with autism spectrum disorders." (PMID 25006883, 2014).
diarrhoea (1 paper, 2017). "We identified a single nucleotide polymorphism (SNP) (rs201253747) c.*61 T > C within the 5-HT4 receptor gene HTR4 to be predominantly present in diarrhoea-IBS patients (IBS-D)." (PMID 29089619, 2017).
myocardial infarction (1 paper, 2023). Gross necrosis of the myocardium, as a result of interruption of the blood supply to the area, as in coronary thrombosis. "Previous investigations have demonstrated that the inhibition of Npr3 improves HF after myocardial infarction in mice, and that Htr4 was involved in the pathogenesis of ischemic HF in rats." (PMID 37762130, 2023).
pulmonary fibrosis (1 paper, 2026). Chronic progressive interstitial lung disorder characterized by the replacement of the lung tissue by connective tissue, leading to progressive dyspnea, respiratory failure, or right heart failure. "Importantly, decreased Htr4 expression might contribute to hypoalveolarization, and the elevated Il-17a expression might be responsible for prenatal DINP exposure-induced pulmonary fibrosis in male offspring." (PMID 42071020, 2026).
small intestinal disease (1 paper, 2021). "In our experiment, NSAID-induced small intestinal disease model rats intervened by berberine showed significantly change in HTR4, F2RL3, NPY, CRHR2, IL1b, VIP, AQP8, NOS1." (PMID 34284820, 2021).
psychiatric disorder (4 papers, 2014 to 2024). A disorder characterized by behavioral and/or psychological abnormalities, often accompanied by physical symptoms. "Alterations in Htr4 expression as a result of higher FA during gestational development may play a role in the genetic predisposition to psychiatric diseases." (PMID 25006883, 2014). "Instead, other groups have previously demonstrated an involvement of Slc22a2 or Htr4 in the efficacy of antidepressant medication, whereas Gabrg2 holds high relevance seen the involvement of GABAergic transmission in several psychiatric disorders." (PMID 27824361, 2016).
tumor (4 papers, 2020 to 2025). "Both HTR1 and HTR4 can, in some tumor types, act through both the MAPK-ERK pathway and the PI3K-AKT-MTOR pathway." (PMID 38136356, 2023). "The TCGA portal showed that the expression of HTR4 in tumor tissues was obviously lower than that in normal tissues." (PMID 35154317, 2022). "Also of note, for some genes, more than one component is present (HTR4 E and S for STES/tumor status, CHIA E and S for LGG/tumor status, AFP E and S for LGG/tumor status)." (PMID 32625238, 2020).
neurological diseases (2 papers, 2018 to 2022). "The alteration in mRNA levels of Htr2a, Htr4, Htr7, Htr5b, Htr6, and Htr3 indicate that serotonin may increase the risk of CJL mediated neurological disorders." (PMID 36582489, 2022).
neurodegenerative disease (1 paper, 2019). A disorder of the central nervous system characterized by gradual and progressive loss of neural tissue and neurologic function. "Also, 5 hydroxytryptamine (serotonin) receptor 4 (Htr4) involved in neurotransmitters production was enhanced, alongside with AdenosineA2a receptor (Adora2), responsible of the development of several neurodegenerative diseases." (PMID 31330819, 2019).
HTR4 also shares sentences with these, for which no sentence is quoted: Cognitive impairment (9 papers); Alzheimer disease (5); cancer (5); cardiac arrhythmia (4); Parkinson disease (4); heart failure (3); Obesity (3); amyloid (2); cognitive decline (2); functional dyspepsia (2); gastrointestinal disorders (2); gastroparesis (2); heartburn (2); lung carcinoma (2); migraine (2); sexual dysfunction (2); age (1); anaplastic astrocytoma (1); anxiety disorder (1); astrocytoma (1); autism spectrum disorder (1); bladder overactivity (1); brain disease (1); cardiac hypertrophy (1); cardiovascular diseases (1); cholangiocarcinoma (1); chronic intestinal pseudo-obstruction (1); cognitive disorder (1); colorectal cancer (1); cystitis (1).
A further 29 diseases each share a sentence with HTR4 in 1 paper.